TRIM31 (tripartite motif containing 31)
Diseases named in the same sentence as TRIM31 in open-access papers (continued):
Sharing a sentence is not in itself a finding about the gene and the disease.
pancreatic cancer (11 papers, 2018 to 2025). "Elevated levels of TRIM31 are associated with more aggressive characteristics and unfavorable outcomes in pancreatic cancer patients." (PMID 39048965, 2024). "High expression of TRIM31 in pancreatic cancer patients is associated with aggressive phenotype and poor prognosis." (PMID 32232394, 2020). "In addition, increased TRIM31 expression was associated with an aggressive phenotype and poor prognosis in pancreatic cancer." (PMID 35054365, 2022). "TRIM31 was markedly upregulated in hepatocellular carcinoma, gallbladder cancer, colorectal cancer, high-grade glioma, pancreatic cancer and acute myeloid leukemia, and the high expression of TRIM31 was also associated with an aggressive phenotype, advanced disease status and poor prognosis." (PMID 36620540, 2022). "Indeed, high TRIM31 expression is associated with an aggressive phenotype and poor prognosis in pancreatic cancer patients." (PMID 30974870, 2019). "In pancreatic cancer cells, TRIM31 has been shown to upregulate nuclear P65 levels and sustain NF-κB activation by promoting K63-linked polyubiquitination of tumor necrosis factor receptor-associated factor 2 (TRAF2)." (PMID 40819060, 2025). "In pancreatic cancer and colorectal cancer, TRIM31 played a role in the activation of the NF-κB and the downstream genes." (PMID 38978046, 2024). "Targeting TRIM31 signaling in pancreatic cancer was suggested to have therapeutic potential, as overexpression of TRIM31 activated NFkB resulting in gemcitabine resistance." (PMID 33311639, 2020). "For instance, enhanced TRIM31 expression could be a positive biomarker for poor clinical outcomes, and TRIM31 confers gemcitabine resistance in pancreatic carcinoma cells by activating the NF-κB pathway." (PMID 37973999, 2023). "As an E3 ubiquitin ligase, TRIM31 promotes K63-linked polyubiquitination of tumor necrosis factor receptor-associated factor 2 (TRAF2) to upregulate the levels of nuclear p65 and then maintains the activation of NF-κB in pancreatic cancer cells." (PMID 36620540, 2022). "Furthermore, TRIM31 promotes gemcitabine resistance in pancreatic cancer cells by activating the NF-κB signaling pathway." (PMID 36620540, 2022). "Furthermore, the ubiquitin proteasome-regulated degradation of TRIM31 was confirmed in AsPC-1 pancreatic cancer cells." (PMID 36620540, 2022). "TRIM31 overexpression confers gemcitabine resistance in pancreatic cancer cells." (PMID 32232394, 2020). "In particular, TRIM31 up-regulates the levels of nuclear p65 by promoting K63-linked polyubiquitination of tumour necrosis factor receptor-associated factor 2 (TRAF2) and sustains the activation of NF-κB in pancreatic cancer cells." (PMID 30974870, 2019). "Inhibition of TRIM31 increases the sensitivity of gemcitabine in pancreatic cancer cells, indicating suppressing TRIM31 could be an effective approach to improve the efficacy of gemcitabine in overcoming chemotherapy resistance in pancreatic cancer." (PMID 39048965, 2024). "Moreover, TRIM31 overexpression confers gemcitabine resistance on pancreatic cancer cells." (PMID 30974870, 2019). "Interestingly, the overexpression of TRIM31 mediates gemcitabine resistance via NF-κB activation, and similarly the inhibition of TRIM31 potentiates the cytotoxic potential gemcitabine both in vitro and in vivo model of pancreatic cancer cells in NF-κB dependent manner." (PMID 30563089, 2018).
gastric cancer (8 papers, 2015 to 2025). A primary or metastatic malignant neoplasm involving the stomach. "TRIM31 promotes gastric cancer cell proliferation and invasion through activating the Wnt/β-catenin pathway by regulating Axin1 protein stability." (PMID 40919166, 2025). "In our study, TRIM31 exhibited significant upregulation in gastric cancer tissues, and this elevated expression was correlated with a poorer prognosis." (PMID 38978046, 2024). "Our research aimed to clarify the correlation between aberrant TRIM31 expression and the Wnt/β-catenin pathway during gastric cancer (GC) oncogenesis and development." (PMID 37973999, 2023). "The TRIM31 protein is polyubiquitinated in gastric cancer, which leads to its proteasomal degradation." (PMID 36620540, 2022). "TRIM31 is upregulated in gastric adenocarcinoma and may be a potential biomarker of gastric cancer because it is overexpressed in the precancerous stage." (PMID 36620540, 2022). "Several studies have demonstrated that TRIM31 enhances the Wnt/β-catenin pathway during the oncogenesis and development of gastric cancer (GC) and acute myeloid leukemia (AML)." (PMID 40919166, 2025). "The level of TRIM31 was influenced by multiple regulatory factors, such as proteasome-mediated degradation and inducible transcription, which may explain its contradictory roles in gastric cancer." (PMID 39768197, 2024). "With increased expression in human gastric cancer tissues and cell lines (BGC-823 and HGC-27), TRIM31 was validated to ubiquitinate Axin1 for degradation to activate the Wnt/β-catenin pathway." (PMID 39768197, 2024). "Aberrant methylation at the genes B3GATL4 (6p21.3), TNXB (6p21.3), TRIM31 (6p21.3), LY6G5C (6p21.33), KIAA1949/PPP1R18 (6p21.3), and GNL1 (6p21.3) identified in NPC was also hypermethylated in EBV-positive gastric cancers compared to EBV-negative gastric cancers (FDR < 1.6 × 10−90)." (PMID 25924914, 2015).
hepatocellular carcinoma (7 papers, 2020 to 2025). A malignant tumor that arises from hepatocytes. "TRIM31 is upregulated in a variety of tumors, such as hepatocellular carcinoma, gallbladder cancer and colorectal cancer, and is associated with an aggressive phenotype, advanced disease status and poor prognosis." (PMID 40919166, 2025). "TRIM31 is an oncogene that has been shown to be overexpressed in different types of cancer, including pancreatic, acute myeloid leukaemia, hepatocellular carcinoma, breast, and CRC." (PMID 35054365, 2022). "TRIM31 expression is significantly up-regulated in hepatocellular carcinoma (HCC) tissues and significantly correlated with advanced disease status." (PMID 32232394, 2020).
colorectal cancer (6 papers, 2021 to 2025). A primary or metastatic malignant neoplasm that affects the colon or rectum. "Upregulated TRIM31 suppressed the sensitivity of daunorubicin and promoted the proliferation of AML cell lines by regulating the Wnt/β-catenin pathway, and the knockdown of TRIM31 caused DNA damage and radiosensitized colorectal cancer cell lines." (PMID 38978046, 2024). "RNAi results for TRIM31 in colorectal cancer cell lines were obtained from the CCLE database utilizing DEMETER252–56." (PMID 35970857, 2022). "The relationship between expression correlation values and TRIM31 dependency was determined in 20 colorectal cancer cell lines." (PMID 35970857, 2022). "Considering most of these genes are involved in viral transcription and viral processes, TRIM31 is likely to play a role in mediating viral transcription and viral processes in colorectal cancer." (PMID 35970857, 2022). "Using the dataset, we performed a pathway enrichment analysis to assess TRIM31 knockdown effect in cellular processes in colorectal cancer cell lines." (PMID 35970857, 2022). "TRIM31 RNAi expression profile obtained from 20 colorectal cancer cell lines using CCLE dataset provided evidence for TRIM31 dependency in these cell lines." (PMID 35970857, 2022). "Interaction network analysis performed following the TRIM31 knockdown in colorectal cancer cell lines highlighted a possible functional role of TRIM31 in viral replication and viral processes." (PMID 35970857, 2022). "TRIM31 is overexpressed in colorectal cancer and facilitates the migration and invasion of colorectal cancer cells via the NF-κB signaling pathway." (PMID 34650049, 2021). "Collectively, our findings suggest that TRIM31 may serve as a key oncogenic factor driving colorectal cancer initiation and progression." (PMID 40819060, 2025). "Moreover, downregulated TRIM31 elevated the level of reactive oxygen species (ROS) and strengthened the apoptosis in colorectal cancer cells." (PMID 38978046, 2024). "In addition, TRIM31 activates the NF-κB pathway to promote migration and invasion in glioma and colorectal cancer." (PMID 36620540, 2022). "Finally, TRIM31 knockdown data obtained from colorectal cancer cell lines resulted in changes in cellular pathways involved in viral replication and viral processes." (PMID 35970857, 2022). "Supporting this hypothesis, further analysis demonstrated that TRIM31 expression was low in normal colorectal tissues, but progressively increased in inflammatory tissues, precancerous lesions, and colorectal cancer tissues, with significantly higher expression in the latter two." (PMID 40819060, 2025). "Hence, targeting TRIM31 may play an important role in preventing SARS-CoV-2 viral infection in colorectal cancer patients." (PMID 35970857, 2022). "In this study, we identified TRIM31, a member of the TRIM family, as significantly upregulated in colorectal cancer (CRC) tissues based on transcriptomic analysis and validation in clinical specimens." (PMID 40819060, 2025). "Taken together, these observations indicate that TRIM31 gene expression is positively correlated with TMPRSS2 and TMPRSS4 in GI cell lines, solid tumors and colorectal cancer PDOs." (PMID 35970857, 2022).
glioma (6 papers, 2020 to 2025). A benign or malignant brain and spinal cord tumor that arises from glial cells (astrocytes, oligodendrocytes, ependymal cells). "Overexpression of TRIM31 is observed in high-grade glioma tissues and associated with short survival time." (PMID 32232394, 2020). "A critical mechanism of chemoresistance in glioma has been attributed to the overexpression of TRIM31, which significantly enhances cell viability and reduces apoptosis following TMZ treatment." (PMID 40740483, 2025). "In gallbladder cancer and glioma, TRIM31 played a carcinogenic role by activating PI3K-Akt pathway and the resistance of chemical agents." (PMID 38978046, 2024). "Multivariate survival analysis demonstrated that TRIM31 was an independent prognostic factor for glioma patients." (PMID 36620540, 2022). "Overexpression of TRIM31 in glioma cell lines enhanced cell proliferation and invasiveness whereas TRIM31 silencing impeded such abilities." (PMID 36139694, 2022). "TRIM31 is an oncogene promoting proliferation, invasion, and migration of glioma cells through Akt and NF-κB pathways." (PMID 32454947, 2020). "TRIM31 was overexpressed in glioma tissues and cell lines compared to normal counterparts." (PMID 36139694, 2022). "In glioma, by silencing or overexpressing TRIM31 expression, the proliferation, invasion and migration of glioma cells could be downregulated or upregulated through the PI3K/Akt signaling pathway." (PMID 36620540, 2022). "Overexpressing TRIM31 promotes the proliferation, invasion and migration of glioma cells." (PMID 32232394, 2020). "TRIM24, TRIM47, TRIM44, TRIM31, TRIM14, TRIM21, and TRIM28 have exhibited significant prognostic value regarding OS and/or PFS of glioma patients." (PMID 36139694, 2022).
acute myeloid leukemia (5 papers, 2020 to 2025). Acute myeloid leukemia (AML) is a group of neoplasms arising from precursor cells committed to the myeloid cell-line differentiation. "TRIM31 regulates Wnt/β-catenin signaling to promote acute myeloid leukemia progression and sensitivity to daunorubicin." (PMID 36620540, 2022). "However, little is known about the relevance of TRIM31 in acute myeloid leukemia (AML)." (PMID 32232394, 2020).
colitis (5 papers, 2016 to 2025). Inflammation of the colon. "On the other hand, TRIM31 deficiency attenuated the severity of dextran sodium sulfate (DSS)-induced colitis by promoting NLRP3 inflammasome activation, which was reported to be possessing protective roles in the model." (PMID 27929086, 2016). "Furthermore, TRIM31 deficiency attenuates the severity of dextran sodium sulfate (DSS)-induced colitis, an inflammatory bowel diseases model in which NLRP3 possesses protective roles." (PMID 27929086, 2016). "However, TRIM31+/+ mice were more susceptible to acute DSS-induced colitis, compared with TRIM31−/− mice." (PMID 27929086, 2016). "A previous study has indicated that TRIM31 is the suppressor of NLRP3 inflammasome in sulfate-induced colitis." (PMID 36597090, 2023). "TRIM31 has been reported to attenuate the activation of NLRP3 inflammasome in sulfate-induced colitis." (PMID 36597090, 2023). "To study the contribution of TRIM31 to the development of colitis, we first assessed the clinical features of age- and sex-matched WT and TRIM31 deficient mice after oral administration of 3% DSS in drinking water." (PMID 27929086, 2016). "TRIM31 expression was downregulated in the DSS-induced colitis model, and NLRP3 expression was upregulated accordingly." (PMID 27929086, 2016). "We thus examined the potential roles of TRIM31 in the DDS-induced colitis model." (PMID 27929086, 2016). "Furthermore, TRIM31 may provide a useful therapeutic target for the intervention of diseases with improper inflammasome activation, such as autoinflammatory diseases, colitis, obesity and diabetes." (PMID 27929086, 2016). "Collectively, these data indicated that TRIM31 played crucial roles in limiting NLRP3 expression and thus exacerbated DSS-induced colitis." (PMID 27929086, 2016). "In TRIM31−/− mice, NLRP3 expression was further increased in the colon of DSS-induced colitis model." (PMID 27929086, 2016).
colorectal tumor (4 papers, 2022 to 2026). "To validate this hypothesis, we examined TRIM31 expression in normal colorectal tissues, intestinal polyps, ulcerative lesions, and colorectal tumor tissues." (PMID 40819060, 2025). "This may therefore be important to develop strategies for targeting TRIM31 particularly in colorectal tumors." (PMID 35970857, 2022).
gallbladder cancer (4 papers, 2021 to 2025). "In gallbladder cancer, TRIM31 promotes proliferation and invasion via the PI3K/Akt signaling pathway." (PMID 36620540, 2022). "Moreover, it’s reported that TRIM31 regulated gallbladder cancer cell proliferation and invasion by suppressing ATK pathway." (PMID 33982666, 2021).
lung carcinoma (4 papers, 2022 to 2025). "The overexpression of TRIM31 was demonstrated as a tumor suppressor that inhibited the proliferation of lung cancer and ovarian cancer cells." (PMID 38978046, 2024). "The expression of TRIM31 in lung cancer cell lines was lower than that in the normal bronchial cell line HBE." (PMID 36620540, 2022). "However, several reports have indicated that TRIM31 is downregulated in cancer; for example, TRIM31 expression is downregulated in lung cancer tissues and cell lines and correlates with clinic-pathological factors." (PMID 36620540, 2022).
non-alcoholic fatty liver disease (4 papers, 2022 to 2025). "Previous studies have reported that TRIM31 plays a critical role in regulating inflammatory responses and is implicated in the pathogenesis of several metabolic diseases, including non-alcoholic fatty liver disease, hypertensive nephropathy, and liver fibrosis." (PMID 40819060, 2025). "Abnormal TRIM31 expression leads to a variety of pathological conditions, such as cancer, innate immunity diseases, sepsis-induced myocardial dysfunction, cerebral ischemic injury, nonalcoholic fatty liver disease and hypertensive nephropathy." (PMID 36620540, 2022).
ovarian carcinoma (4 papers, 2016 to 2024). A malignant neoplasm originating from the surface ovarian epithelium. "Similarly, TRIM31 is a tumor suppressor gene in breast and ovarian cancer." (PMID 37958599, 2023).
HCMV infection (3 papers, 2016 to 2022). "Since we previously showed an aberrant low-level expression of TRIM31 in patients with Crohn's disease, we speculated that HCMV infection affects TRIM31 expression in intestinal epithelial cells." (PMID 27216961, 2016). "Meanwhile, cytomegalovirus (HCMV) infection significantly downregulated the expression of TRIM31 and thus inhibited the clearance of intracellular Shigella, which may explain the reason for positive correlation of IBD severity with HCMV infection." (PMID 35361231, 2022). "Remarkably, HCMV infection unambiguously downregulated endogenous TRIM31 expression in a dose-dependent manner, but not LC3." (PMID 27216961, 2016).
inflammatory bowel disease (3 papers, 2016 to 2025). A spectrum of small and large bowel inflammatory diseases of unknown etiology. "In contrast, in inflammatory bowel disease models where NLRP3 exerts a protective role, TRIM31 deficiency conversely alleviates disease severity." (PMID 40819060, 2025).
liver fibrosis (3 papers, 2024 to 2025). "TRIM31 is also responsible for the antifibrotic effects of mulberrin (a bioactive phytochemical from the traditional Chinese medicine Ramulus Mori) in CCl4-induced liver fibrosis." (PMID 38206764, 2024).
non-small cell lung carcinoma (3 papers, 2017 to 2023). A group of at least three distinct histological types of lung cancer, including non-small cell squamous cell carcinoma, adenocarcinoma, and large cell carcinoma. "In addition, TRIM31 plays a potential tumor suppressor role in non-small cell lung cancer." (PMID 36620540, 2022).
colon cancer (2 papers, 2022 to 2024). "Five TRIM expression was significantly upregulated (TRIM14, TRIM15, TRIM24, TRIM29, and TRIM31), and the other five TRIM genes showed decreased expression (TRIM1, TRIM3, TRIM9, TRIM22, and TRIM73) in both colon cancer (COAD) and rectal cancer (READ)." (PMID 38769340, 2024).
depression (2 papers, 2024 to 2025). "However, this CpG site is 877 bp upstream of TRIM31 (chr6:30,070,674-30,080,867), which is associated with cognitive performance/intelligence, memory, unipolar depression, ASD and schizophrenia, all of which are epidemiologically associated with PCE." (PMID 39277688, 2025). "For instance, one study indicated that XYS might inhibit neuroinflammation to treat depression by regulating the TRIM31/NLRP3 inflammasome." (PMID 39185306, 2024).
gastritis (2 papers, 2023). Inflammation of the stomach. "Together, our data identified that TRIM31 negatively regulated the activation of NLRP3 inflammasome in Hp-associated gastritis by affecting ROS and autophagy of gastric epithelial cells." (PMID 36597090, 2023). "Confirming this, our data revealed that the mRNA and protein expression of TRIM31 was significantly downregulated in mice with Hp-associated gastritis." (PMID 36597090, 2023). "In summary, the current study points out that TRIM31 attenuates NLRP3 inflammasome activation in Hp-associated gastritis by affecting ROS and autophagy." (PMID 36597090, 2023). "Recent studies have found that tripartite motif-containing 31 protein (TRIM31) attenuated NLRP3 inflammasome activation in H. pylori-associated gastritis by affecting ROS and autophagy." (PMID 37833958, 2023). "Our study showed that TRIM31 was downregulated in Hp-associated gastritis." (PMID 36597090, 2023). "TRIM31 may act as a novel possible therapeutic target for Hp-associated gastritis." (PMID 36597090, 2023).
hypertensive nephropathy (2 papers, 2022 to 2025). Kidney damage that results from chronically elevated blood pressure; complications include glomerular damage resulting in proteinuria and hematuria. "Additionally, TRIM31 promotes the proteasomal degradation of MAP3K7 in the TGF-β1 signaling pathway, which plays a key role in hypertensive nephropathy." (PMID 40819060, 2025).